SIRT3 (sirtuin 3)
Diseases named in the same sentence as SIRT3 in open-access papers (continued):
Sharing a sentence is not in itself a finding about the gene and the disease.
cardiovascular diseases (continued). "In cardiovascular diseases, the study revealed that diabetic mice with a deletion of SIRT3 displayed exacerbated cardiac dysfunction, excessive ROS accumulation, increased activation of the NLRP3 inflammasome, and an increased LDH level in the serum." (PMID 38067543, 2023). "Sirt3 is a mitochondrial deacetylase and shows protective effects in diverse cardiovascular diseases." (PMID 37760018, 2023). "An increasing number of studies indicate that sirtuin-3 (SIRT3) participates in the development of cardiovascular diseases." (PMID 36691640, 2023). "Accumulating evidence confirms that SIRT3 attenuation or ablation accelerates the development of aging-related diseases, including cancers, metabolic syndromes, cardiovascular diseases, and neurodegenerative diseases." (PMID 36056557, 2022). "In this part, we reviewed mitochondrial biogenesis with SIRT3 in three major aging-related diseases: cardiovascular diseases, neurodegenerative diseases, and T2DM." (PMID 36056557, 2022). "SIRT3 is a kind of mitochondrial protector that can prevent cardiovascular diseases because it participates in their metabolism and dynamics by regulating the acetylation of mitochondrial proteins." (PMID 36614171, 2022). "Enhanced inflammation caused by ROS accumulation plays an important role in the progression of cardiovascular disease, and SIRT3 regulates mitochondrial function by regulating ROS metabolism and maintains normal cardiac function." (PMID 35855865, 2022). "SIRT3 is an important transcriptional factor involved in the regulation of cardiovascular diseases and mitochondrial fatty-acid oxidation." (PMID 35635037, 2022). "Under pathological conditions, Sirt3 deletion-mediated mitochondrial disorders are involved in the development of human cardiovascular diseases." (PMID 34095262, 2021). "SIRT4 overexpression in NRCMs decreased SIRT3-mediated MnSOD deacetylation and decreased its activity, promoting ROS accumulation during hypertrophic stress-inducing cardiovascular disorders." (PMID 34685718, 2021). "Particularly SIRT3, already involved in the regulation of cellular energy metabolism, in cardiovascular diseases and in the control of apoptosis, has recently emerged as a novel regulator of mitochondrial metabolism and function too." (PMID 33182469, 2020). "In rodents, increased expression of Sirt3 in cardiomyocytes was found in the early phase of cardiovascular disorders, but Sirt3 expression was decreased in human failing hearts." (PMID 30042676, 2018). "Further research is warranted to better understand the putatively protective role of Sirt3 in human cardiovascular disease." (PMID 27071400, 2016). "Our study provides evidences for further researches on the role of SIRT3 in cardiovascular diseases." (PMID 26223796, 2015). "SIRT3 is also involved in scavenging ROS and inhibits oxidative stress in cardiovascular diseases." (PMID 36691640, 2023). "Furthermore, mounting studies suggested that SIRT3 plays an essential role in regulating cell death, autophagy, and metabolic homeostasis in cardiovascular diseases." (PMID 36691640, 2023). "SIRT3 is a histone deacetylase to regulate cardiac cell growth, energy metabolism, reactive oxygen species production, inflammation and cell death, and, thus, it plays a vital role in cardiovascular diseases." (PMID 36671063, 2023). "Sirt3 has an important impact on mitochondrial fission and fusion in cardiovascular disease." (PMID 35592397, 2022). "Sirt3 has a wide range of substrates and is closely related to cardiovascular diseases." (PMID 34095262, 2021). "Studies have shown that SIRT3 plays a protective role in cardiovascular diseases." (PMID 32575874, 2020). "The activation of SIRT3 may represent a promising therapeutic strategy to improve mitochondrial function and treat related cardiovascular diseases." (PMID 32973538, 2020).
cardiovascular diseases (continued). "Although SIRT3-mediated cardiovascular diseases have been intensively investigated and our understanding of the biology of SIRT3 has expanded remarkably over the past decade, the role of SIRT3 in endothelial metabolism and coronary microvascular dysfunction has not been well-studied." (PMID 30873415, 2019). "Sirt3 has protective effects in many cardiovascular diseases." (PMID 31139646, 2019). "A growing number of studies portraying SIRT3 as a key regulator of mitochondrial metabolism and energetics highlight the necessity to develop new pharmacological compounds and conditional approaches targeting SIRT3 for treatment of cardiovascular diseases." (PMID 30131726, 2018). "In conclusion, these studies have demonstrated the important role of SIRT3 in cardiovascular disease and may be a new target for the treatment of cardiovascular disease, but the specific mechanism by which SIRT3 ameliorates myocardial tissue injury in DCM patients remains to be refined." (PMID 41276460, 2025). "Moreover, SIRT3 plays an important role in a wide range of biological activities such as energy homeostasis, apoptosis, inflammation and it can be used for protection against cardiovascular diseases and heart failure." (PMID 33182469, 2020). "Therefore, SIRT3 may be involved in development of cardiovascular diseases through pathways of metabolism, inflammation and others." (PMID 27078640, 2016). "SIRT1, SIRT3, and SIRT6 have been shown to provide protective effects in various cardiovascular disease models, by decreasing inflammation, improving metabolic profiles or scavenging oxidative stress." (PMID 34712151, 2021). "Interestingly, several studies have identified other sirtuins (mainly SIRT3 and SIRT6) to provide beneficial effects in cardiovascular diseases and energy metabolism." (PMID 35204314, 2022). "Sirt3, a metabolic sensor, can use intracellular metabolites such as NAD+ and acetyl-CoA for modulating mitochondrial function to match nutrient supply which plays a crucial role in cardiovascular diseases." (PMID 36405744, 2022). "Studies found that Sirt3 increases the anti-oxidant capacity of cells by deacetylating mitochondrial proteins including SOD2 in age-related diseases such as neurodegenerative diseases and cardiovascular diseases." (PMID 34249264, 2021). "Lack of SIRT3 in experimental animal leads to several age-related diseases, including cardiovascular diseases." (PMID 27078640, 2016).
neurodegenerative disease (53 papers, 2010 to 2025). A disorder of the central nervous system characterized by gradual and progressive loss of neural tissue and neurologic function. "Several regulated genes, such as Arpc3, Glp2r, Sirt3 and Per1 have been reported to exert protective effects in neurodegenerative diseases or reverse memory deficits in various models, underlining the observed protective effects of spermidine." (PMID 35780157, 2022). "SIRT3 is the only sirtuin that specifically plays a role in extending lifespan in humans and is associated with neurodegenerative diseases." (PMID 33541361, 2021). "The present data largely support the safety of SIRT3-oriented therapies, in terms of susceptibility to infections, for treating metabolic, oncologic and neurodegenerative diseases." (PMID 28634345, 2017). "Sirt3 reveals a connection between mitochondrial metabolism promoting the Warburg effect, tumorigenesis and induction of oxidative stress associated with randomly accumulated lesions causing degenerative diseases and ageing." (PMID 29257069, 2017). "Here, we review the up-to-date signaling pathways and molecular mechanisms by which SIRT3 regulates the biology of aging and age-associated diseases, especially cardiovascular and neurodegenerative diseases, and how interventions that target these pathways could improve health and increase lifespan." (PMID 34829803, 2021). "Further investigation of the roles of SIRT3 in other neurodegenerative diseases involving mitochondrial dysfunction will provide novel insights into the therapeutic potential of this target." (PMID 39976201, 2025). "SIRT3 expression is reduced in ad, and activating SIRT3 is a potential therapeutic approach for neurodegenerative diseases." (PMID 40125832, 2025). "This in vivo efficacy provides convincing proof-of-concept for SIRT3-targeted neuroprotection, underscoring the therapeutic potential of macrocyclic SIRT3 activators in neurodegenerative disease." (PMID 40430438, 2025). "In conclusion, these findings highlight the promising therapeutic potential of HKL as a novel SIRT3-targeted agent for the prevention or even reversal of cardiac, pulmonary, and neurodegenerative diseases." (PMID 40860195, 2025). "While SIRT3 to SIRT5 are known to be located in the mitochondrial matrix, only SIRT3 has been associated with neurodegenerative diseases through its regulation of calcium homeostasis." (PMID 40003583, 2025). "Activating SIRT3 is a potential therapy for age-related brain abnormalities and neurodegenerative diseases." (PMID 39091611, 2024). "SIRT3, a mitochondrial deacetylase, plays a pivotal role in regulating mitochondrial function and protecting neurodegenerative diseases." (PMID 38572816, 2024). "Although SIRT3’s functions in peripheral tissues are well established, the significance of its downregulation in neurodegenerative diseases is beginning to emerge." (PMID 36675125, 2023). "SIRT3 can inhibit mitochondrial dysfunction, reduce the production of ROS, induce mitophagy, and inhibit apoptosis; therefore, it can be used to treat neurodegenerative diseases." (PMID 38001861, 2023). "Modulation of SIRT3 activity now represents a powerful strategy for treating neurodegenerative diseases." (PMID 38001861, 2023). "Many of the enriched pathways in our KEGG analysis were also related to neurodegenerative diseases and based on the previous studies, Sirutin 3 (SIRT3) is one of the common genes among these pathways." (PMID 37482618, 2023). "Many of these mechanisms are closely related to neurodegeneration, implying that Sirt3 is a key regulatory molecule in neurodegenerative diseases." (PMID 37238605, 2023). "Because of its role in brain homeostasis, several studies have reported SIRT3 downregulation in the following neurodegenerative diseases." (PMID 36675125, 2023). "Overall, SIRT3 has certain impacts on neurodegenerative diseases through the modulation of mitochondrial dynamics." (PMID 36056557, 2022).
neurodegenerative disease (continued). "Based on the roles of SIRT3 in mitochondrial function, we further reviewed the involvement of SIRT3 in mitochondrial quality control in the nervous system, and especially in neurodegenerative diseases." (PMID 31780922, 2019). "In this part of our review, we studied three major neurodegenerative diseases—AD, PD, and HD—and summarized the regulation of mitochondrial quality control by SIRT3 in each disease." (PMID 31780922, 2019). "This review summarizes recent research into mitochondrial quality control and the role of SIRT3 in mitochondrial function, and further illustrates the effects of SIRT3 on mitochondrial quality control in the neurodegenerative diseases AD, PD, and HD." (PMID 31780922, 2019). "Modern evidence suggests the critical role of SIRT3 in the progression of several metabolic and neurodegenerative diseases." (PMID 29324783, 2018). "Compelling evidence has shown that Honokiol, a SIRT3 activator, expresses many beneficial effects in neurodegenerative diseases." (PMID 29324783, 2018). "Previous studies have shown that SIRT3 expression is significantly decreased in degenerative diseases." (PMID 30420619, 2018). "Inhibiting mPTP opening has been proposed as a neuroprotective strategy for a number of neurodegenerative diseases, and one proposed mechanism for SIRT3-mediated cytoprotection involves it inhibiting the opening of the mPTP." (PMID 30090057, 2018). "Inflammatory processes in human macrophages are also mediated by SIRT3 and inflammation is another shared feature of neurodegenerative diseases, including ALS and HD." (PMID 28603486, 2017). "Of the three mitochondrial SIRTs (SIRT3, 4, and 5), some evidence correlates SIRT3 with neurodegenerative disease." (PMID 27226812, 2016). "Taken together, these data strongly support the protective role of SIRT3 against oxidative stress in a variety of cell types and murine models of various degenerative diseases." (PMID 26370974, 2015). "SIRT3 is upregulated by elevated levels of ROS during excitotoxic stress, a common feature of neurodegenerative diseases, such AD." (PMID 24093018, 2013). "Since oxidative stress and energetic failure contribute to neurodegeneration, the roles of Sirt3 in controlling ROS generation and maintaining energy homeostasis have profound implications for intervention of neuronal death by neurodegenerative diseases." (PMID 21390294, 2011). "However, SIRT3 levels, and thus activity, declines with age, and is further decreased in pathologies such as cardiac myopathy, fatty liver disease, and neurodegenerative diseases, such as Alzheimer’s, Huntington’s and Parkinson’s disease." (PMID 39157755, 2024). "Indeed, there is a large body of evidence to suggest that increasing SIRT3 activity has protective effects, which has been shown to be of therapeutic benefit in cell and animal models of cardiovascular, renal, liver and neurodegenerative diseases." (PMID 39157755, 2024). "AMPK and SIRT3 are key molecules of aging and related degenerative diseases." (PMID 36846717, 2023). "Therefore, these diverse actions of SIRT3 make it a suitable candidate to target for the treatment of AD and other neurodegenerative diseases." (PMID 36675125, 2023). "SIRT3 deacetylates and activates several mitochondrial proteins, its actions are seen in diverse pathways that are relevant in the pathogenesis of AD and other neurodegenerative diseases." (PMID 36675125, 2023). "Meanwhile, activation of the SIRT3-FOXO3a pathway could protect mitochondria from oxidative stress, thereby ameliorating lung senescence and neurodegenerative diseases." (PMID 36192726, 2022). "Therefore, our current study and these reports highlighted above suggest that ALS is a neurodegenerative disease characterized by systemic NAD+ deficiency that can benefit from NAD+ supplementation and/or SIRT3 activation." (PMID 33184465, 2021). "In this way, SIRT3 may be protective regarding the pathogenesis of almost all neurodegenerative diseases." (PMID 32380741, 2020).
neurodegenerative disease (continued). "Moreover, there is a link between sirtuin-3 (SIRT3) and neurodegenerative diseases in relation to AMPK." (PMID 33276674, 2020). "In addition to the role of SIRT3 in mitochondrial quality control in neurodegenerative diseases, recent studies have gradually started to investigate the roles of two other mitochondrial sirtuins, SIRT4 and SIRT5, in mitochondrial quality control." (PMID 31780922, 2019). "The Sirt3 signal pathway has been studied in neurodegenerative diseases." (PMID 30362958, 2018). "Mitochondrial SIRT3 is also regulated by various stresses in neurodegenerative diseases." (PMID 24093018, 2013). "This constitutes the first demonstration of Sirt3 involvement in AD neurodegenerative disease." (PMID 23139766, 2012). "Recent studies have also shown that SIRT3 has a role in mitochondrial quality control, including the refolding or degradation of misfolded/unfolded proteins, mitochondrial dynamics, mitophagy, and mitochondrial biogenesis, all of which are part and parcel of neurodegenerative diseases." (PMID 32380741, 2020). "Recent studies have also shown that SIRT3 has a role in mitochondrial quality control, including in the refolding or degradation of misfolded/unfolded proteins, mitochondrial dynamics, mitophagy, and mitochondrial biogenesis, all of which are affected in neurodegenerative diseases." (PMID 31780922, 2019). "Emerging findings also suggest that SIRT3 and mitochondrial metabolism may be important in attenuating the deleterious effects of oxidative stress in a variety of cell types and murine models of degenerative diseases." (PMID 26370974, 2015).
metabolic disease (45 papers, 2009 to 2026). A congenital disorder (due to inherited enzyme abnormality) or acquired (due to failure of a metabolically important organ) disorder resulting from an abnormal metabolic process. "Sirt3 is one of the key factor in counteracting aging, which plays an important role in alleviating aging‐associated metabolic diseases on heart, kidney, neuron, and liver." (PMID 39348266, 2024). "Conversely, downregulation or impairment of SIRT3 has been associated with various pathological conditions, including metabolic disorders, neurodegenerative diseases, and cancer." (PMID 39329773, 2024). "Modulation of SIRT3 activity has been proposed as a promising therapeutic target for ameliorating metabolic diseases and associated cardiac disturbances." (PMID 32296036, 2020). "Further work showed that SIRT3 knockout mice were more susceptible to hepatic lipid accumulation and the development of metabolic disorders, suggesting that hyperacetylation of hepatic fatty acid oxidation enzymes reduced their activity (4, –, 7)." (PMID 30323061, 2018). "NR can protect mitochondrial homeostasis through increasing the enzymatic activity of Sirtuin 1 (Sirt1) and Sirtuin 3 (Sirt3) in skeletal muscle and brown adipose tissue, and has a protective effect against the development of metabolic diseases caused by a high-fat diet (HFD)." (PMID 37373163, 2023). "There is an ultimate need for further exploration into how SIRT3’s regulatory functions can be harnessed to mitigate conditions like reproductive aging and metabolic disorders that impair oocyte quality." (PMID 39329773, 2024). "Sirtuin-3 (Sirt3) is the primary protein deacetylase in mitochondria and plays a crucial role in mitochondrial quality control, which is affected in age-related and metabolic diseases." (PMID 35054859, 2022). "For instance, OS causes metabolic disorders by affecting the regulation of PPARα, AMPK/mTOR, and SIRT3/FOXO3a." (PMID 35784531, 2022). "Divided into 4 classes, SIRT1 and SIRT3 are categorized into class I, which primarily encompasses involvement in metabolic diseases and FA oxidation." (PMID 35042927, 2022). "3-TYP, a selective SIRT3 inhibitor, reversed AEDC effect on autophagy, indicating that AEDC inhibited NLRP3 inflammasome activation to ameliorate inflammation-related metabolic disorders by promoting autophagy via SIRT3." (PMID 33796528, 2021). "Rodents and humans demonstrate the critical role of SIRT3 in metabolic diseases, highlighting the decrease in SIRT3 activity in several tissues such as the liver, the adipose tissue and the muscle." (PMID 33121167, 2020). "In our recent review, we provided insight into the involvement of sirtuin-3 (SIRT-3), a member of the mitochondrial sirtuin family, in metabolism dysfunctions, suggesting its putative bridge role between metabolic diseases and HCC." (PMID 30917505, 2019). "Our results provide fundamental information to reveal the cat SIRT1 and SIRT3 function about relationship of metabolic diseases." (PMID 24073959, 2013). "Given the critical role of SIRT3 in maintaining mitochondrial function, elucidating its regulatory role in cellular metabolism is essential for understanding the connection between mitochondrial dysfunction and metabolic disorders." (PMID 41304967, 2025). "KDM5B binds to the SIRT3 promoter and its overexpression triggers mitochondrial metabolism disorders and oxidative stress by directly inhibiting SIRT3 expression through demethylating H3K4me3 or indirectly repressing the AMPK pathway-regulated SIRT3 expression." (PMID 39062577, 2024). "SIRT3 can safeguard the kidneysagainst metabolic disorders through various mechanisms." (PMID 38261767, 2024). "SIRT3 is essential for maintaining mitochondrial function, and it has been verified to regulate aging, neurodegeneration, liver and heart diseases, and other metabolic diseases." (PMID 38370354, 2024).